GPD1L (glycerol-3-phosphate dehydrogenase 1 like)
Diseases named in the same sentence as GPD1L in open-access papers (continued):
Sharing a sentence is not in itself a finding about the gene and the disease.
glucose metabolism disorders (1 paper, 2025). "Among the remaining 11 genes associated with CVS, GPD1L and GPD2, both involved in glucose metabolism, stand out, suggesting a potential link between glucose metabolism disorders and CVS." (PMID 39981435, 2025).
kidney tumour (1 paper, 2023). "The results of our study from kidney tumour samples and adjacent normal samples showed that the expression of GPD1L was decreased in RCC and positively correlated with prognosis in RCC." (PMID 37382962, 2023). "The results consistently indicated that the expression of GPD1L was decreased in kidney tumour samples and tumour cell lines compared with adjacent nontumour kidney tissues and normal kidney cells at both the mRNA and protein levels." (PMID 37382962, 2023).
non-small cell lung carcinoma (1 paper, 2023). A group of at least three distinct histological types of lung cancer, including non-small cell squamous cell carcinoma, adenocarcinoma, and large cell carcinoma. "For example, in non-small cell lung cancer, GPD1L is involved in the regulation of cell polarity, metabolic reprogramming, and tumorigenesis." (PMID 37685919, 2023).
osteoarthritis (1 paper, 2020). A noninflammatory degenerative joint disease occurring chiefly in older persons, characterized by degeneration of the articular cartilage, hypertrophy of bone at the margins and changes in the synovial membrane. "And NEAT1 impeded the progression of osteoarthritis via the regulation of miR-181a-GPD1L axis." (PMID 32280304, 2020).
triple-negative breast carcinoma (1 paper, 2020). An invasive breast carcinoma which is negative for expression of estrogen receptor (ER), progesterone receptor (PR), and human epidermal growth factor receptor 2 (HER2). "A similar oncogenic hypoxic circuit, in which the role of SDHD is replaced by glycerol-3-phosphate dehydrogenase 1-like (GPD1L), has been shown to be involved in the apoptosis of triple-negative breast cancer cells." (PMID 32014012, 2020).
cancer (13 papers, 2016 to 2026). A tumor composed of atypical neoplastic, often pleomorphic cells that invade other tissues. "We discovered a new gene called GPD1L that was associated with cancer and found that its expression was aberrant in a wide variety of cancers." (PMID 37035759, 2023). "In addition to its role in HCC, GPD1L has also been implicated in other solid tumours, indicating its broader relevance in cancer biology." (PMID 37685919, 2023). "GPD1L, a member of the glycerol-3-phosphate dehydrogenase family, has emerged as a potential tumour suppressor gene, with high expression associated with a favourable prognosis in various cancers." (PMID 37685919, 2023). "Interestingly, GPD1L acts as a tumour suppressor in many other cancers, where high expression levels are associated with a favourable prognosis." (PMID 37685919, 2023). "Over the past several years, growing studies have indicated that GPD1L was involved in the advancement of a number of different cancers." (PMID 37035759, 2023). "In this study, following an examination of the TGCA datasets, we found that GPD1L displayed a dysregulated state in a wide variety of cancers; this led us to believe that GPD1L is an essential regulator in the progression of malignancies." (PMID 37035759, 2023). "GPD1L has been shown to participate in cell proliferation, migration and apoptosis by regulating oxidative stress in cancer." (PMID 36064558, 2022). "Additionally, GPD1L expression has been shown to be downregulated in certain types of cancer, such as head and neck squamous cell carcinoma and renal cell carcinoma." (PMID 38689091, 2024). "Next, we conducted a pan-cancer analysis using TCGA data to investigate GPD1L expression patterns." (PMID 37685919, 2023). "The inverse relationship between high GPD1L expression and poor prognosis in HCC, contrasting with other cancers where high expression is associated with a favourable prognosis, highlights the need for further investigation into the underlying molecular mechanisms." (PMID 37685919, 2023). "Previous researches had uncovered the roles that GPD1L played in a number of different cancers." (PMID 37035759, 2023). "Furthermore, the expression pattern of GPD1L was shown to be variable in various types of cancers, which led researchers to hypothesize that GPD1L might act as tumor promoters or tumor suppressors." (PMID 37035759, 2023). "Our analysis revealed 9 shared genes, with UBE2C, POLQ, RAD51, and HOXB7 being up-regulated and EDNRB, GPD1L, F10, SORBS2, and CXCL12 down-regulated in both cancers." (PMID 41790655, 2026). "Apart from GPD1L and CYGB, miR-210-3p can target several other genes in cancers, such as FGFRL136, SIN3A37, and EphrinA338." (PMID 32908121, 2020). "The down-regulation of GPD1L by miR-210 occurs in vivo and contributes to HIF1 stability, which enhance the metastatic and invasiveness of cancer." (PMID 31367490, 2019). "In the second dataset all the CGC genes (5/507) were classified as oncogenes by OncoScore and 4 (4/302) out of 5 nCan genes (ALMS1, DCAF17, GPD1L and WFS1) were classified as ‘non-cancer’ at the final time point, as expected." (PMID 28387367, 2017). "Deregulations of miR-21 and miR-130b, as well as deregulation of GPD1L, HLF, HPGD and MGLL have been reported either in HNOC or other cancer types, and these MRMs represent significant functional relevance in OTSCC." (PMID 27561985, 2016).
tumor (11 papers, 2015 to 2025). "We initially investigated the association between the tumour GPD1L gene expression and clinical outcomes in HCC." (PMID 37685919, 2023). "Clinical studies have demonstrated that higher GPD1L expression in HCC is associated with an advanced tumour stage, larger tumour size, increased microvascular invasion, and reduced overall and disease-free survival rates." (PMID 37685919, 2023). "Analysis of Hallmark gene sets revealed that GPD1L-high tumours were enriched for gene sets associated with G2M checkpoint, epithelial-mesenchymal transition (EMT), and E2F target genes." (PMID 37685919, 2023). "Meanwhile, when compared with normal group, the HSPA6, NOTCH3 and PKP2 expression were significantly increased in LUAD tumor group, but GPD1L and SMAD9 expression were dramatically decreased in control group (all P < 0.001)." (PMID 40796704, 2025). "Mechanistically, the dichotomous pathway activation—immune/ECM remodeling in GPD1L-low versus metabolic regulation in GPD1L-high tumors —suggests GPD1L modulates tumor-stroma crosstalk." (PMID 40538846, 2025). "Compared to the control group, serum levels of HSPA6 and NOTCH3 were significantly elevated in the CRC tumor group, whereas GPD1L, PKP2, and SMAD9 exhibited a marked decrease." (PMID 40796704, 2025). "Overall, these consistent findings across independent datasets indicate that GPD1L gene expression is prognostic in HCC and support existing evidence that GPD1L expression is a marker of aggressive tumours." (PMID 37685919, 2023). "The protective effect of GPD1L against redox stress, particularly mitochondrial stress, suggests its potential in adapting to the high metabolic demands observed in certain tumours." (PMID 37685919, 2023). "In contrast, pathways related to bile acid synthesis, fatty acid metabolism, and oxidative phosphorylation were found to be downregulated in GPD1L-high tumours." (PMID 37685919, 2023). "Similar findings in vivo also supported this concept, showing that GPD1L suppressed tumour growth by promoting PINK1‐mediated mitophagy." (PMID 37382962, 2023). "Overall, these findings suggest a positive selection for GPD1L overexpression in HCC that correlates with tumour progression." (PMID 37685919, 2023). "The cell line drug testing data should be further validated in patient-derived HCC-tumour organoids characterised by GPD1L expression." (PMID 37685919, 2023). "GPD1L exhibited increased expression and promoter demethylation with advancing tumour stage, confirming positive selection during tumorigeneses." (PMID 37685919, 2023). "Single-cell RNA sequencing analysis also revealed a notable expression of GPD1L within the tumour microenvironment, particularly in natural killer (NK) and T cells." (PMID 37685919, 2023). "Specifically focusing on HCC, GPD1L mRNA levels were found to be increased in tumour tissues relative to adjacent normal tissue in 13 out of 18 HCC datasets." (PMID 37685919, 2023). "In order to explore the molecular characteristics associated with GPD1L overexpression, we conducted differential gene expression analysis comparing high and low GPD1L mRNA tumours using the TCGA dataset." (PMID 37685919, 2023). "For example, the dysregulation of metabolic pathways observed in GPD1L-high tumours suggests the involvement of metabolic reprogramming in GPD1L-mediated tumorigenesis." (PMID 37685919, 2023). "Compared with the tumour group, the expression of GPD1L in the normal group was much higher in the GEO datasets." (PMID 37382962, 2023). "Studies done in the past have found evidences that GPD1L was involved in more than one type of tumor." (PMID 37035759, 2023). "Compared with the vector group, the tumour volume and tumour weight were significantly decreased in the GPD1L‐overexpressing group." (PMID 37382962, 2023).
tumor (continued). "GPD1L acts as tumor suppressor in cancers; one mechanism is to inhibit the activity of prolyl hydroxylase (PHD), which hydroxylates prolines in HIF-1α and promotes its proteasome degradation." (PMID 32908121, 2020). "GPD1L downregulation represents a hallmark of CRC progression, with affecting the expression of HIF-1α and MMP9 significantly impeding malignant behaviors, nominating it as a candidate tumor suppressor in colorectal neoplasia." (PMID 40538846, 2025). "In addition, the expression of serum HSPA6, NOTCH3 and PKP2 were significantly up-regulated in the LUAD tumor group, while GPD1L and SMAD9 showed a significant down-regulation trend when compared to the control group." (PMID 40796704, 2025). "Furthermore, GPD1L plays a role in dysregulated lipid metabolism, a hallmark of HCC, influencing lipid synthesis, lipolysis, and mitochondrial function, which impact tumour cell proliferation, survival, and metastatic potential." (PMID 37685919, 2023). "Moreover, GPD1L prevented tumour growth and promoted mitophagy by activating the PINK1/Parkin pathway in vivo." (PMID 37382962, 2023). "Interestingly, GPD1L mRNA levels showed an incremental increase, while promoter methylation exhibited a decrease with advancing tumour stage in HCC." (PMID 37685919, 2023). "Finally, while the five biomarker proteins (HSPA6, NOTCH3, PKP2, SMAD9, and GPD1L) are primarily intracellular, their presence in serum could potentially be attributed to tumor derived extracellular vesicles or cell lysis during tumor progression." (PMID 40796704, 2025). "In the CRC tumor group, the expression levels of HSPA6 and NOTCH3 protein were dramatically up-regulated, while GPD1L, PKP2, and SMAD9 protein were dramatically down-regulated (all P < 0.05)." (PMID 40796704, 2025). "The results showed that, compared to normal samples, HSPA6 and NOTCH3 were dramatically increased, while GPD1L, PKP2, and SMAD9 were dramatically decreased in tumor samples in both the CRC training dataset and the CRC validation dataset (all P < 0.05)." (PMID 40796704, 2025). "External validation using GEO datasets revealed consistent patterns: GSE74602 (30 tumor-normal pairs, P<0.001) and GSE113513 (14 pairs, P<0.001) both exhibited decreased GPD1L in malignant tissues." (PMID 40538846, 2025). "The result demonstrated a significant increase in HSPA6 and NOTCH3 expression, but a significant decreased in GPD1L, PKP2 and SMAD9 in CRC tumor group when compared to those in normal group (all P < 0.001)." (PMID 40796704, 2025). "Our multi-platform analysis of TCGA and GEO datasets revealed consistent GPD1L downregulation in CRC tissues compared to normal mucosa, a finding validated in our institutional cohort (n=58 tumor-normal pairs)." (PMID 40538846, 2025). "At the molecular level, altered GPD1L expression and activity have been observed in HCC tissues compared to adjacent non-tumour liver tissues." (PMID 37685919, 2023). "The expression of miR-205-5p (p < 0.0001) and UBE2C (p = 0.0093) were upregulated in tumor tissues, while the expressions of miR-140-3p (p = 0.0293), PTPRM (p < 0.0001), GPD1L (p = 0.0002), and FOXF2 (p < 0.0001) were downregulated in tumor tissues." (PMID 35712349, 2022). "Similarly, in the LUAD tumor group, HSPA6, NOTCH3, and PKP2 protein expression were dramatically stimulated, whereas GPD1L and SMAD9 protein expression were dramatically suppressed (all P < 0.05)." (PMID 40796704, 2025). "Similarly, PKP2 and GPD1L retained significance in LUAD, supporting their utility as biomarkers even when accounting for tumor progression." (PMID 40796704, 2025). "Moreover, compared to normal samples, HSPA6, NOTCH3, and PKP2 were dramatically overexpressed, while GPD1L and SMAD9 were dramatically de-expressed in tumor samples in both the LUAD training dataset and the LUAD validation dataset (all P < 0.05)." (PMID 40796704, 2025).
tumor (continued). "Comparative analysis revealed a marked elevation of GPD1L expression in non-neoplastic tissues relative to tumor specimens (P<0.001)." (PMID 40538846, 2025). "Moreover, IHC staining was performed on the subcutaneous tumor tissues of mice in which YTHDC1 was downregulated, and it was found that OIP5 expression was lower in the kd-YTHDC1 group, while GPD1L expression was increased." (PMID 38573528, 2024). "It is speculated that GPD1L overexpression in HCC may be a consequence of promoter demethylation and the wider E2F dysfunction with advancing tumour stage, where GPD1L itself is an E2F3 target." (PMID 37685919, 2023). "When considered alongside the clinical, pathological, and gene enrichment data, we speculate that heightened GPD1L expression is prompted to sustain membrane GPL biosynthesis in rapidly proliferating, aggressive HCC tumours, contributing to an overall lipid metabolic reprogramming." (PMID 37685919, 2023). "Importantly, we discovered that the level of GPD1L expression was significantly lower in LUAD specimens compared to nontumor specimens, which suggested that it might play a role as a tumor suppressor gene in the evolution of LUAD." (PMID 37035759, 2023).
GPD1L also shares sentences with these, for which no sentence is quoted: cardiomyopathies (2 papers); hepatocellular carcinoma (2); lung adenocarcinoma (2); lung carcinoma (2); atrial fibrillation (1); breast carcinoma (1); cardiac conduction disorder (1); cardiovascular disorder (1); central obesity (1); conduction disorder (1); diabetes mellitus (1); esophageal squamous cell carcinoma (1); glioma (1); head and neck squamous cell carcinoma (1); heart failure (1); hepatic cancer (1); hepato-biliary tumours (1); long QT syndrome (1); melanoma (1); oropharyngeal cancer (1); renal cell carcinoma (1); sudden cardiac death (1).